PPARG (peroxisome proliferator activated receptor gamma)
Diseases named in the same sentence as PPARG in open-access papers (continued):
Sharing a sentence is not in itself a finding about the gene and the disease.
myocardial ischemia (22 papers, 2008 to 2025). A disorder of cardiac function caused by insufficient blood flow to the muscle tissue of the heart. "Accordingly, experimental animal studies using myocardial ischemia/reperfusion experiments all reported beneficial aspects with PPARγ activators." (PMID 36768666, 2023). "Among eight miRNAs, miRNA-292-5p, which participates in myocardial ischemia–reperfusion injury by activating the peroxisome proliferator-activated receptor-α/-γ (PPARα/PPARγ)-dependent signaling pathway, has been studied since 2018." (PMID 36266609, 2022). "Many studies showed that NF-κB competes with PPARγ in inflammation and myocardial ischemia–reperfusion injury." (PMID 34950652, 2021). "There is plenty of evidence showing the antagonistic or competing biological functions of nuclear factor-kappa B (NF-κB) and PPARγ in inflammation, nephrotoxicity, and myocardial ischemia–reperfusion injury." (PMID 34950652, 2021). "The group of J. L. Mehta concentrated on the interplay of PPARγ and the renin-angiotensin system in myocardial ischemia." (PMID 33322384, 2020). "We investigated the potential of telmisartan to improve microvascular dysfunction induced by myocardial ischemia/reperfusion (I/R) injury by activating the peroxisome proliferator-activated receptor gamma (PPARG) pathway." (PMID 23738781, 2013). "Additionally, recent findings demonstrated that carvacrol attenuated isoproterenol-induced myocardial ischemia via activation of PPARγ and Nrf2, along with downregulation of NLRP3." (PMID 40430456, 2025). "This study intends to explore whether CMP mediates the protective effect of PPARγ on myocardial ischemia-reperfusion injury by combining the regulatory effect of myocardial peptide on PPARγ." (PMID 39744161, 2025). "The PPARγ-Nrf2 pathway inhibits myocardial ischemia-reperfusion injury." (PMID 35517804, 2022). "It appears that cardiac PPARγ expression may play an important though poorly understood role in cardiac physiology, and it is possible that modulation of PPARγ signaling may affect the response to cardiac ischemia." (PMID 18648539, 2008). "Therefore, we speculate that PPARG may be an essential target for regulating Dgat2 expression, and this potential regulatory pathway may provide a novel therapeutic strategy for myocardial ischemia-reperfusion injury, which is worthy of further investigation." (PMID 40510478, 2025). "Although no specific reports regarding the effects of β-sitosterol on HIRI were found, β-sitosterol has been shown to prevent myocardial ischemia–reperfusion injury (MIRI) both in vivo and in vitro, potentially through the regulation of the PPARγ/NF-κB signaling pathway." (PMID 38001230, 2023).
papillary thyroid carcinoma (22 papers, 2004 to 2025). "PAX/PPARγ fusion rearrangement has an inactivating effect on the tumour-suppressor gene PPARγ and is found in 30–60% of FTC and in 38% of the follicular variant of papillary thyroid cancer (FVPTC)." (PMID 37374164, 2023). "In contrast, stimulation of PPARγ signaling leads to ER inhibition and induces apoptosis in papillary thyroid cancer cells." (PMID 36114448, 2022). "Previous studies showed that PPARγ mRNA is downregulated in papillary thyroid cancer cells compared to the normal thyroid tissue, benign nodule, follicular and anaplastic thyroid cancers." (PMID 29085335, 2017). "Moreover, a new PPAR-γ ligand inhibits TGF-β1-induced EMT, migration, and invasion of papillary thyroid carcinoma cells through the p38 MAPK signaling pathway in a PPARγ-dependent manner." (PMID 37048080, 2023). "A number of gene alterations, such as point mutations in RAS and BRAF genes, point mutations or amplification of PIK3CA, and fusion genes involving RET, NTRK1 and PPARγ are known to frequently occur in differentiated thyroid carcinoma, and are correlated to different morphological subtypes." (PMID 22087789, 2011). "This review summarizes hypotheses on the role of PPARγ in tumors, on cellular targets of TZDs, antitumor effects of monotherapy and of TZDs in combination with other compounds, with a focus on their role in the treatment of differentiated thyroid carcinoma." (PMID 25866814, 2015). "Papillary thyroid carcinomas with a predominantly follicular pattern were more often PPARγ negative than classic PTCs (80% vs 28%; P=0.01)." (PMID 15238980, 2004). "Cytopathologic diagnosis was suspicious for papillary thyroid carcinoma and ThyroSeq molecular testing revealed an underlying CREB3L2::PPARγ fusion, implying a high risk for “malignancy or non-invasive follicular thyroid neoplasm with papillary-like nuclear features (NIFTP)”." (PMID 40839045, 2025).
autoimmune disease (21 papers, 2009 to 2025). A disorder resulting from loss of function or tissue destruction of an organ or multiple organs, arising from humoral or cellular immune responses of the individual to their own tissue constituents. "Studies on the association between PPARG polymorphisms and the severity of autoimmune diseases have revealed mixed results." (PMID 27221351, 2016). "More importantly, human CD4 T cells from healthy controls and MS patients were strongly susceptible to PPARγ-mediated suppression of Th17 differentiation, suggesting that PPARγ is a promising molecular target for specific immunointervention in Th17-mediated autoimmune diseases such as MS." (PMID 21234105, 2010). "In summary, PPARγ agonists abolish Th17 responses through inhibiting glutaminolysis, thereby ameliorating Th17 cell-related inflammation and autoimmune diseases." (PMID 33754076, 2021). "This miRNA targets the 3′-UTR of high mobility group box-1 (HMGB1), a protein with increased expression in many autoimmune diseases, and through miR-142-3p, PPARγ thus contributes to maintaining reduced HMGB1 expression." (PMID 34638914, 2021). "Gender-based differences in therapeutic strategies using PPARγ agonists and combination treatments with estrogen should be considered for the treatment of autoimmune diseases." (PMID 27335315, 2016). "PPARγ has been highlighted in T cell responses and autoimmune diseases and PPARγ ligand treatment has been shown to inhibit effector T cell functions in vitro and in vivo." (PMID 27335315, 2016). "Accordingly, PPARγ activation by agonists offers an important strategy for the treatment of autoimmune diseases." (PMID 27548145, 2016). "Although PPARγ agonists have effective immunoregulatory capacity in many autoimmune diseases and transplant rejection animal models, the side effects of conventional thiazolidinedione drugs (TZD) have been reported in recent clinical studies." (PMID 25383620, 2014). "Previous studies have also suggested that PPARγ is an important therapeutic target for treating autoimmune disease." (PMID 24921943, 2014). "The compound also enhanced PPARγ mRNA expression indicating this new compound as promisor in inflammatory and autoimmune diseases treatment, mainly by reducing IL-17A levels in RA cells." (PMID 24078927, 2013). "Th17 cells play important roles in autoimmune diseases and a recent study showed that PPARγ selectively inhibits Th17 differentiation." (PMID 19888466, 2009). "Taken together, these results highlight the importance of the epigenetic modulation of PPARγ in autoimmune diseases such as lupus, the protective role of TLR-Sirt1-PPARγ signalling in SLE, and the therapeutic potential of targeting this pathway and histone deactelyases in SLE." (PMID 34638914, 2021). "In addition to the synthetic ligands, various types of polyunsaturated fatty acid (PUFA) metabolites can serve as endogenous ligands for PPARγ to ameliorate inflammatory responses and autoimmune diseases." (PMID 27335315, 2016). "Taken together, our data demonstrated that reduction of Pparg expression in T-helper cells is critical for spontaneous SLE-like autoimmune disease development; we also revealed a novel function of PPARγ in lymphocyte trafficking and cross talk between Th17 and B cells." (PMID 27221351, 2016). "Dietary intake of these metabolites could be an advantageous strategy, especially for females, to prevent autoimmune diseases by stimulating PPARγ to regulate sensitive TFH responses." (PMID 27335315, 2016). "Our previous study found that PPARγ activation with eicosapentaenoic acid can impact the balance between Th17/Treg cells and protect cardiac allografts, consistent with its effect on autoimmune diseases." (PMID 25383620, 2014). "The role of PPARγ in B cells in autoimmune diseases is less well documented." (PMID 23983678, 2013).
autoimmune disease (continued). "The success of this approach has led to the potential use of PPARγ ligands as therapeutic agents in human autoimmune disease, even with the knowledge that these compounds may target molecule other than PPARγ." (PMID 19888466, 2009). "In infection models and autoimmune disease models, EZH2 inhibits the expression of genes and signaling pathways involved in anti-inflammatory function, such as PPARγ, SOCS1, STAT6, etc.." (PMID 35432300, 2022). "Four DEGs (SOD2, GATA3, PPARG, and MAPK14) were related to various functional categories, including “inflammatory response”, “cell activation”, “autoimmune disease”, and “vascular endothelial cell”." (PMID 34026343, 2021). "Modulating PPARγ to dampen abnormal T cell activation and TFH cell mediated GC reaction can be exploited for treating autoimmune diseases." (PMID 24921943, 2014). "The activation of PPARγ enhances Treg responses through up-regulating CD36/CPT1-mediated fatty acid oxidation and subsequent N-glycan branching of TβRII/IL-2Rα, which is beneficial for inflammatory and autoimmune diseases." (PMID 35392915, 2022). "In this study, by the age of 14 mo, PpargC/− mice with PPARγ expression at 25% of the normal level exhibited high autoantibody levels and developed mesangial proliferative glomerulonephritis, which resembled systemic lupus erythematosus (SLE)-like autoimmune disease." (PMID 27221351, 2016). "Regardless of the sex-dependent roles of PPARγ, pioglitazone treatment suppressed the differentiation of Th17 cells in both male and female T cells, suggesting that PPARγ is an important target to modulate Th17-mediated autoimmune diseases." (PMID 27548145, 2016).
endometriosis (21 papers, 2013 to 2026). The growth of functional endometrial tissue in anatomic sites outside the uterine body. "The endometriosis risk allele A of rs2921188 (OR= 1.13, 95% CI: 1.05–1.21), P = 5.9× 10−4) in PPARG (peroxisomeproliferator-activated receptor gamma) is associated with increased WHRadjBMI(β = 0.017; P = 1.1× 10−3)." (PMID 25296917, 2015). "Patients with endometriosis had higher levels of peroxisome proliferator-activated receptor gamma (PPARγ) than all women with other causes of infertility." (PMID 23956867, 2013). "The genetic association between PPARG and endometriosis has been demonstrated." (PMID 33623786, 2021). "Using a co-culture system, we simulated a cholesterol-abundant ectopic milieu and demonstrated cholesterol induced M2 macrophage polarization via the STAT6/PPARγ pathway, connecting cholesterol metabolism to immune response in endometriosis." (PMID 41362733, 2026). "Treatment with rosiglitazone, a PPARγ agonist, in a rat model of endometriosis significantly reduced VEGF levels, thus decreasing blood vessel formation in endometriotic tissues." (PMID 39803270, 2025). "PPARγ plays a pivotal role in the pathogenesis of endometriosis by modulating key biologic pathways, such as inflammation, angiogenesis, and apoptosis." (PMID 39803270, 2025). "Transcriptional studies in endometriosis model rats treated with resveratrol have shown that PPARγ activation is pivotal in mediating the anti‐inflammatory and metabolic regulatory effects of the flavonoid." (PMID 39803270, 2025). "Pioglitazone, another PPARγ agonist, was shown to reduce the levels of RANTES, a chemokine associated with inflammation, in patients with endometriosis." (PMID 39803270, 2025). "With PPARG expression being induced by endometriosis sEVs, we aimed to assess the effect of pharmacological activation of PPARG on CD36 and the macrophage phenotype." (PMID 39062452, 2024). "In particular, PPARγ staining levels were significantly lower in the deep infiltrating endometriosis patient group." (PMID 38690174, 2024). "Surprisingly enough, the PPARγ agonist succeeded in significantly reducing the height, width, length, and spherical volumes, of endometriosis in the studied rat model." (PMID 38690174, 2024). "In regards to PPAR expression in endometriosis, PPARγ seems to represent the most studied PPAR isoform in endometriosis and to influence various pathways involved in the disease onset and progression." (PMID 38690174, 2024). "Resveratrol treatment induces PPARγ activation in ectopic focus of endometriosis, while telmisartan up-regulates PPARγ in peritoneal endometriosis-like lesions with consecutive anti-inflammatory and anti-proliferative effects." (PMID 38690174, 2024). "PPARG agonist treatment was proposed for endometriosis as it appeared to prevent or reduce some of its features." (PMID 39062452, 2024). "In peritoneal lesions, the pain reported by endometriosis patients increased as PPARγ expression augmented." (PMID 38690174, 2024). "PCR examination results revealed that PPARγ activity was higher in the abdominal wall endometriosis compared to the eutopic endometrium." (PMID 38690174, 2024). "A sample of the abdominal endometriosis and uterine endometrium underwent Reverse Transcriptase quantitative Polymerase Chain Reaction (RT-qPCR) examination of PPARγ mRNA expression." (PMID 38690174, 2024). "For endometriotic lesions, the PPARG gene governing glucose metabolism and fatty acid storage, which is important for the development of endometriosis was upregulated." (PMID 34367125, 2021). "Nevertheless, the limited number of studies focusing on the different interactions of PPARγ agonists in endometriosis restricts its clear and immediate use as a therapeutic strategy." (PMID 34204039, 2021). "Future clinical trials are needed to better investigate and highlight the role of PPARγ agonists in endometriosis." (PMID 34204039, 2021).
endometriosis (continued). "In this case we found that the abdominal wall endometriosis express PPARγ activity and its value is higher compared to eutopic endometrium." (PMID 30384143, 2018). "Each samples was measured three times and the median expression of PPARγ mRNA expression is 21.85 ng/μl for eutopic endometrium and 26.84 ng/μl for abdominal wall endometriosis." (PMID 30384143, 2018). "A sample of the abdominal endometriosis and eutopic endometrium was sent for PCR examination of PPARγ mRNA expression." (PMID 30384143, 2018). "Further studies separating epithelial tissue and stroma can be performed to prove the role of PPARγ in the pathogenesis of endometriosis." (PMID 30384143, 2018). "•The ectopic abdominal wall endometriosis express higher PPARγ activity compared to eutopic endometrium." (PMID 30384143, 2018). "In uterus, PPARG activation inhibits growth and survival of human endometriosis cells by suppressing estrogen biosynthesis." (PMID 26429873, 2015). "In summary, our results demonstrated that cholesterol accumulation in endometriotic lesions directly promotes ESCs proliferation and invasion, and stimulates M2 macrophage polarization via the STAT6/PPARγ signaling pathway, creating a microenvironment conducive to endometriosis progression." (PMID 41362733, 2026). "This reduction in inflammation was associated with improved implantation rates in patients undergoing in vitro fertilization (IVF), suggesting that PPARγ activation could help create a more favorable reproductive environment for those with endometriosis." (PMID 39803270, 2025). "Similarly, resveratrol, another flavonoid, has been extensively studied for its role in regulating PPARα and PPARγ activity in endometriosis models." (PMID 39803270, 2025). "As such, the current article constitutes an up-to-date review comprehensive of the literature about the effects of the PPAR isoforms PPARα and PPARγ in endometriosis establishment and progression, alongside their potential as eventual anti-endometriotic treatment targets." (PMID 38690174, 2024). "In the case of PPARG, macrophages treated with sEVs from endometriosis also showed higher expression levels than those treated with sEVs from controls, although in this case, it was not accompanied by any change in the expression of CD36, one of the genes commonly induced by PPARG activation." (PMID 39062452, 2024). "The most studied PPAR in endometriosis is undoubtedly PPARγ." (PMID 38690174, 2024). "Intense staining of PPARγ expression was induced by high dose resveratrol treatment in glandular epithelial cells in the lesion tissues of model rats, hence inducing PPARγ activation in ectopic focus of endometriosis-induced rats." (PMID 38690174, 2024). "An interesting finding was the induction of PPARG in macrophages treated with endometriosis sEVs." (PMID 39062452, 2024). "Interestingly enough, the exact location and extent of the endometriosis seems to have an influence on the PPARγ expression pattern." (PMID 38690174, 2024). "PPARγ undoubtedly represents the most studied PPARγ isoform in endometriosis." (PMID 38690174, 2024). "Thus, the purpose of this review is to summarize the potential actions of PPARγ agonists in endometriosis by acting on inflammation, angiogenesis, invasion and adhesion, and apoptosis." (PMID 34204039, 2021). "PPARγ agonists can suppress the vascular adhesion molecule expression in endometriosis." (PMID 34204039, 2021). "This indicates that Sunitinib may act as PPARγ agonists, modulating lipid metabolism and inflammation and improve insulin sensitivity to suppress endometriosis development." (PMID 34367125, 2021). "Several animal models have shown the interest of PPARγ agonists in endometriosis." (PMID 34204039, 2021). "Thus, the purpose of this review is to summarize the potential actions of PPARγ agonists in endometriosis by acting on inflammation, angiogenesis, invasion, adhesion, and apoptosis." (PMID 34204039, 2021).
endometriosis (continued). "Interestingly, resveratrol was also able to induce the expression of peroxisome proliferator-activated receptor gamma (PPARγ), whose agonists are emerging as a potential therapy in endometriosis due to its effect on the reduction of inflammation, adhesion, angiogenesis, and induction of apoptosis." (PMID 38612425, 2024). "Patients with endometriosis tend to have altered levels of PPARγ, with both ovarian endometriomas and deep infiltrating endometriosis showing significantly reduced immunoreactivity against PPARγ, but PPARγ activity being higher in abdominal wall endometriosis than in the eutopic endometrium." (PMID 38690174, 2024). "Consequently, we opted to pharmacologically activate PPARG by treating macrophages with rosiglitazone to investigate whether this PPARG agonist could reverse the shift to the M2 phenotype promoted by endometriosis sEVs." (PMID 39062452, 2024). "In the complex microenvironment of endometriosis, except for exerting a direct promoting impact on EESCs, cholesterol drives the polarization of macrophages towards the M2 phenotype through the STAT6/PPARγ signaling pathway." (PMID 41362733, 2026). "And in endometriosis, PPARγ activation suppresses the biosynthesis of estrogen and prostaglandin D2 (PGD2) signalling and thereby inhibits the growth and survival of human endometriotic cells (endometriosis) in murine and baboon models." (PMID 40225034, 2025). "Peritoneal fluid from patients with endometriosis activated U937 cells which had been transiently transfected with a PPARα reporter, whereas it did not successfully activate PPARγ constructs." (PMID 38690174, 2024).